SNORD105B (small nucleolar RNA, C/D box 105B)
Gene: Small nucleolar RNA gene on chromosome 19 (10,109,757 to 10,109,835, forward strand). Ensembl gene ENSG00000238531.
Gene Ontology:
Biological process: RNA processing
Cellular component: nucleolus
Homologues: Orthologues: chimpanzee SNORD105B (97% identical), pig SNORD105B (89% identical), macaque SNORD105B (85% identical), dog SNORD105B (84% identical), rat Snord105b (76% identical), mouse Gm23008 (71% identical).